CTSV (cathepsin V)
Diseases named in the same sentence as CTSV in open-access papers (continued):
Sharing a sentence is not in itself a finding about the gene and the disease.
lung carcinoma (continued). "The mass spectrometry experiment showed that the N-glycosylation locus of CTSV are N221 and N292, glycosylated CTSV (band 43 kDa) was particularly expressed in lung cancer samples and correlated with lymph node metastasis." (PMID 35494076, 2022). "Collectively, these results showed that CTSV is upregulated in lung cancer and is correlated with poor overall survival, implying the oncogenic role of CTSV." (PMID 35494076, 2022). "Collectively, these results supported that glycosylation of CTSV is required for secretion, thereafter determine the metastasis behavior of lung cancer cells." (PMID 35494076, 2022). "Here, we analyzed GEO database and found that lung cancer presented high expression of cathepsin V (CTSV)." (PMID 35494076, 2022). "Together, the results suggested that CTSV is exclusively N-glycosylated at N221 and N292 in lung cancer cells." (PMID 35494076, 2022). "Mutation of the N221 and N292 residues with Q residues, generating N221Q and N292Q, decreased the glycosylation of CTSV, thereby inhibited the secretion of CTSV, and remarkably suppressed the metastasis, invasion and migration of lung cancer cells." (PMID 35494076, 2022). "Our study reveals glycosylated CTSV holds promise for providing effective prognostic biomarker for lung cancer patients." (PMID 35494076, 2022). "The functional impact and mechanism of the dysregulation of CTSV in lung cancer remain to be determined." (PMID 35494076, 2022). "To this end, we isolated serum from the plasma of lung cancer patients and healthy donors, the level of CTSV in circulating serum was significantly higher in patients with lung cancer than that in healthy donors." (PMID 35494076, 2022). "We then performed immunohistochemistry assay in 73 paired lung cancer tissues and normal lung tissues and confirmed that CTSV is overexpressed in lung cancer and correlates with poor prognosis." (PMID 35494076, 2022). "Additionally, CTSV, which plays a role in apoptosis and lung cancer metastasis, and PMAIP1, a key pro-apoptotic regulator, showed significantly elevated expression in the treatment group." (PMID 40143009, 2025). "According to the findings, lung cancer is one type of tumor with elevated CTSV expression." (PMID 38078882, 2023). "Our earlier findings suggest that CTSV blocking may be a useful treatment option for a minority of lung cancer patients with metastases." (PMID 38078882, 2023). "Furthermore, CTSV reduces T cell function in vitro, and CTSV antibody inhibition significantly reduces lung cancer metastasis." (PMID 38078882, 2023). "We also demonstrated that CTSV inhibition reduces lung cancer metastasis in vivo." (PMID 38078882, 2023). "CTSV acts as a driver in the metastasis of lung cancer both in vitro and in vivo." (PMID 38078882, 2023). "A recent study has reported that CTSV in serum is a prognosis biomarker in lung cancer." (PMID 38078882, 2023). "Notably, in an in vivo lung cancer metastasis model using the stable cell line A549-luciferase, CTSV knockdown significantly reduced lung and distant metastases." (PMID 38078882, 2023). "We conducted co-culture experiments using lung cancer cells to examine the impact of CTSV depletion on T cell responses to identify whether CTSV regulates the activity of T cells." (PMID 38078882, 2023). "Collectively, our findings suggest that glycosylated CTSV could be a sensitive biomarker for lung cancer patients with metastasis." (PMID 35494076, 2022). "Together, the data suggested that the level of CTSV in serum distinguished lung cancer patients from healthy donors, revealing that the level of CTSV in serum (glycosylation CTSV) might be a biological marker for lung cancer." (PMID 35494076, 2022). "Notably, serum (secreted) CTSV distinguished lung cancer patients from healthy donors, and glycosylated CTSV determined its secretion and pro-metastatic role in lung cancer." (PMID 35494076, 2022).
lung carcinoma (continued). "Notably, the level of CTSV in serum distinguished lung cancer patients from healthy donors and the glycosylated 43 kDa CTSV (secreted CTSV) is associated with lymph node metastasis." (PMID 35494076, 2022). "Importantly, the Elisa detection in serum of 12 lung cancer patients and 12 healthy donors showed that the level of CTSV in serum distinguished lung cancer patients from healthy donors." (PMID 35494076, 2022). "Together, the results suggested that the level of glycosylation CTSV (band 43 kDa) might be a more sensitive prognostic marker for lung cancer patients with metastasis." (PMID 35494076, 2022). "In addition, analysis of GEO datasets (GSE31210, GSE19188 and GSE3269) showed that lung cancer exhibits high CTSV levels." (PMID 35494076, 2022). "In conclusion, our research showed that CTSV is upregulated in lung cancer and correlated with a poor prognosis, indicating that CTSV might be a prognostic biomarker for lung cancer." (PMID 35494076, 2022). "Cysteine cathepsins are pivotal in disease development and progression; they have been reported to be overexpressed in a number of cancers and to lead to increased cancer cell invasion and metastasis, however, many facets of CTSV activity in lung cancer remain uncharacterized." (PMID 35494076, 2022). "Whilst previous studies have associated CTSV expression with distant metastasis and postulated that CTSV is a liver-tropic gene in lung cancer, no studies have been undertaken as yet to determine the contribution of CTSV to the metastatic process." (PMID 33298139, 2020). "Hence, CTSV blockade increased T-cell activity and improved lung cancer cell apoptosis." (PMID 38078882, 2023). "Overall, our findings indicated that CTSV downregulates adhesion molecules such as fibronectin, E-cadherin, and N-cadherin, which may suggest that CTSV is a potential therapeutic target for halting lung cancer spread." (PMID 38078882, 2023). "Moreover, the high CTSV expression group showed lower levels of the StromalScore (Spearman R = −0.319), ImmuneScore (Spearman R = −0.403), and EstimateScore (Spearman R = −0.388) than that when compared with low expression CTSV group in lung cancer." (PMID 38078882, 2023). "It is still unknown how the dysregulation of CTSV in lung cancer functions and how it works." (PMID 38078882, 2023). "In addition, we found that a higher protein level of the first glycosylation band (band 43 kDa) in lung cancer patients was correlated with lymph node metastasis (P=0.0173), while no significant changes were observed in the second and third bands (39 kDa and 37 kDa) of CTSV." (PMID 35494076, 2022). "Mechanistic studies showed that only glycosylated CTSV (43-kDa band) are secreted to extracellular matrix (ECM) and promoted the metastasis of lung cancer." (PMID 35494076, 2022). "Interestingly, different from a previous study, we found that both glycosylation sites N221 and N292 of CTSV, rather than N292 alone, are important for its secretion, this regulating its promoting effect on tumor metastasis in lung cancer." (PMID 35494076, 2022).
bladder cancer (4 papers, 2021 to 2025). "Overall, our findings indicated that CTSV was expressed abnormally in bladder cancer tissues and that high CTSV expression was associated with a poor prognosis in bladder cancer patients." (PMID 35443863, 2022). "As expected, CTSV overexpression resulted in increased activity of the NF-κB pathway, and we further confirmed this association using the qPCR analysis in CTSV-silenced bladder cancer cells." (PMID 35443863, 2022). "CTSV is upregulated and promotes proliferation through the NF-κB pathway in bladder cancer and may be a potential target in inflammation-associated bladder cancer." (PMID 35443863, 2022). "To test whether the increased mRNA level of CTSV was associated with poor prognosis in bladder cancer, we carried out Kaplan–Meier analysis from GEPIA online tool." (PMID 35443863, 2022). "The results showed that CTSV-depleted cells could significantly decrease the colony number and size, suggesting that its deficiency could cause attenuation in the bladder cancer cell viability." (PMID 35443863, 2022). "The results showed that the overexpressed CTSV remarkably increased the colony number and size, suggesting that CTSV facilitated bladder cancer cell viability." (PMID 35443863, 2022). "On the contrary, the deletion of CTSV significantly inhibited the proliferation and viability of bladder cancer cells." (PMID 35443863, 2022). "Here, we demonstrated that CTSV facilitated cell proliferation and viability by overexpressing or knocking out the CTSV gene in different bladder cancer cell lines." (PMID 35443863, 2022). "Although the emerging evidence shows a pro-oncogenic role of CTSV in cancer development, its expression pattern and role in bladder cancer are still elusive." (PMID 35443863, 2022). "On the other hand, CRISPR/Cas9 mediated CTSV silencing in the T24 bladder cancer cell line attenuated the cell viability and proliferation in the bladder cancer that had high expression of CTSV." (PMID 35443863, 2022). "In short, our data showed that CTSV as an oncogene contributed to the proliferation and viability in bladder cancer cell lines." (PMID 35443863, 2022). "In summary, our data demonstrated that CTSV is an important oncogene that participated in the development and progression of bladder cancer." (PMID 35443863, 2022). "The results showed that CTSV-mRNA expression was upregulated in the bladder cancer tissues compared to that of the normal tissues." (PMID 35443863, 2022). "Here, we found that CTSV is dramatically increased in bladder cancer tissues when compared to normal tissues." (PMID 35443863, 2022). "The TCGA database analysis suggested that the aberrant expression of cathepsin V (CTSV) was related to a poor outcome in bladder cancer patients." (PMID 35443863, 2022). "To determine the function of CTSV in the progression of bladder cancer, we first quantified the CTSV expression in a pan of bladder cells." (PMID 35443863, 2022). "The immunoblotting analysis detected the expression of CTSV protein both in wild-type and targeted knockout cells, which showed a successful depletion of CTSV in the T24 bladder cancer cell line." (PMID 35443863, 2022). "The results showed that the bladder cancer patients with high CTSV levels had remarkably poorer overall and disease-free survival rates than the patients with lower levels of CTSV, suggesting a potential role of CTSV in the development and progression of bladder cancer." (PMID 35443863, 2022). "The colony formation and growth curve assays showed that CTSV overexpression could increase the bladder cancer cell viability and proliferation." (PMID 35443863, 2022). "Thus, through the overexpression and deletion of CTSV, we are the first to clarify the role of CTSV in bladder cancer development and progression, suggesting CTSV to be a potential target in bladder cancer." (PMID 35443863, 2022).
bladder cancer (continued). "Additionally, CTSV is also involved in triggering the inflammatory signaling pathway, and its high expression in bladder cancer patients indicates a poor prognosis." (PMID 35443863, 2022). "We firstly assessed the expression of CTSV in bladder cancer cells." (PMID 35443863, 2022). "Besides, the cell growth curve assay showed that CTSV-knockout decreased the cell growth ability, thus, repressing bladder cancer cell proliferation." (PMID 35443863, 2022). "The overexpression of CTSV increased the proliferation and viability of bladder cancer cells." (PMID 35443863, 2022). "Moreover, PDTC, a specific target in the NF-κB signaling, inhibited CTSV induced NF-κB activation and bladder cancer cell growth." (PMID 35443863, 2022). "Our study suggested a pro-oncogenic role of CTSV in bladder cancer, which could be used as a biomarker and potential target in the study of bladder cancer." (PMID 35443863, 2022). "As a result, it is proposed that CTSV depletion could inhibit the tumorigenesis ability of bladder cancer cells." (PMID 35443863, 2022). "In summary, using a series of bioinformatics and retrospective analyses, the present study identified a subset of seven genes (CDC20, CDKN2A, CTSV, FOXM1, KRT23, MAGEA6, and S100A9), which were significantly associated with progression and prognosis of bladder cancer." (PMID 34885040, 2021). "Kaplan-Meier data showed that a higher CTSV expression could decrease the overall survival and disease-free survival of BCa patients, indicating an important role of CTSV in bladder cancer progression, which could be used as a potential prognostic biomarker and therapeutic target in bladder cancer." (PMID 35443863, 2022). "The PPI network analysis of three databases identified the following subsets of DEGs, including CDC20, CDKN2A, CTSV, FOXM1, KRT23, MAGEA6, and S100A9, which were significantly upregulated in bladder cancer." (PMID 34885040, 2021). "The expression profile of CDC20, CDKN2A, CTSV, FOXM1, KRT23, MAGEA6, and S100A9 were significantly higher in bladder cancer specimens compared with normal bladder tissue in patients." (PMID 34885040, 2021). "CDKN2A, CTSV and FOXM1 with 95.5% sensitivity and 100% specificity in predicting bladder cancer progression." (PMID 34885040, 2021). "Although the emerging evidence shows a pro-oncogenic role of CTSV in cancer development, the biological functions of CTSV in bladder cancer have not been characterized yet." (PMID 35443863, 2022). "A total of seven genes, including CDKN2A, CDC20, CTSV, FOXM1, MAGEA6, KRT23, and S100A9 were confirmed with strong prognostic values in bladder cancer and validated by qRT-PCR conducted in various human bladder cancer cells representing stage-specific disease progression." (PMID 34885040, 2021). "Furthermore, the study also revealed a three-panel gene set (CDKN2A, CTSV, and FOXM1) that can accurately predict tumor progression and suggested as potential prognostic biomarker(s) for bladder cancer, which could aid in clinical decision making." (PMID 34885040, 2021).
hepatocellular carcinoma (4 papers, 2020 to 2025). A malignant tumor that arises from hepatocytes. "We also observed that knocking down CTSV in vitro inhibited the proliferation and migration of hepatocellular carcinoma." (PMID 39695350, 2024). "Both cathepsin V and mRNA expression were higher in hepatocellular carcinoma than in normal liver tissue, and immunohistochemical results showed that high cathepsin V expression was associated with shorter OS and DFS." (PMID 36797681, 2023). "We also discovered a natural small molecule medication that can target the lysosomal core target protein CTSV via molecular docking, and we confirmed in vitro that knocking down CTSV decreases the proliferation and invasion of hepatocellular carcinoma cell lines." (PMID 39695350, 2024). "Finally, we demonstrated in vitro that knocking down the CTSV gene dramatically reduced the proliferation and migration of hepatocellular carcinoma." (PMID 39695350, 2024). "Therefore, we studied the biological role of CTSV in hepatocellular cancer." (PMID 39695350, 2024). "LAPTI, composed of four lysosome‐related genes (CTSV, LAPTM4B, DNAJC6, AP1M2), is a reliable prognostic indicator for hepatocellular carcinoma patients and is validated in external data sets." (PMID 39695350, 2024).
breast tumor (3 papers, 2019 to 2025). "Genes associated with breast tumor invasion (CTSV, MMP11) were significantly abundant in sub-population III with OR2W3 upregulation compared to other sub-populations." (PMID 31551495, 2019). "We have discovered that CTSV is localised to the nuclear compartment in breast tumour cells, mediated by a bipartite nuclear localisation signal (NLS) within the CTSV sequence and that nuclear CTSV is required for cell cycle progression and histone stability in breast tumour cells." (PMID 38026973, 2023). "CD109, AHNAK2, and MFGE8 in breast BRCA1-mut cancers, and B3GNT7, CTSV, and GSDMC in BRCA2-mut breast tumors." (PMID 40647506, 2025).
endometrial cancer (3 papers, 2020 to 2025). Primary or metastatic malignant neoplasm involving the endometrium (mucous membrane that lines the endometrial cavity).
liver cancer (3 papers, 2022 to 2025). An epithelial or non-epithelial malignant neoplasm that arises from the liver. "High CTSV expression is associated with enhanced invasion and metastasis of tumor cells in various cancers, such as breast and liver cancer." (PMID 40666516, 2025). "The expression levels of MYBL2, SPP1, CTSV and EPO were remarkably increased in liver cancer cells compared with normal liver cells, while the expression level of CYP2C9 was significantly decreased (p < 0.05)." (PMID 36650832, 2023). "Univariate and multivariate Cox regression analyses showed that the expression of CTSV, CXCL8, MKI67 and PRF1 were independent prognostic factors in liver cancer patients." (PMID 35902905, 2022).
thyroid carcinoma (3 papers, 2022 to 2023). "Previous studies in thyroid carcinoma cells suggested that CTSV trafficking to the nucleus was most abundant during S phase of the cell cycle." (PMID 38026973, 2023). "CTSV, also known as CTSL2, has been shown to be present in the nuclei of thyroid carcinoma cells and suggested that it promotes S‐phase progression, while CTSB supports chromosome segregation during mitosis." (PMID 35203107, 2022). "In thyroid cancer, E2F1 overexpression can lead to cathepsin V upregulation." (PMID 36147668, 2022).
breast invasive carcinoma (2 papers, 2020 to 2023). "In summary, cathepsin V seems to play an important role in the progression from DCIS towards invasive breast cancer." (PMID 36002710, 2023). "In silico analysis of the relationship between CTSV mRNA expression and GATA3 protein expression was also examined in clinical samples, using the TCGA 2012 breast invasive carcinoma dataset via cBioPortal." (PMID 33298139, 2020).
glioma (2 papers, 2023). A benign or malignant brain and spinal cord tumor that arises from glial cells (astrocytes, oligodendrocytes, ependymal cells). "Thus, we performed quantitative real-time PCR (qRT-PCR) analyses, which confirmed that CTSH, CTSO, CTSF, CTSK, CTSS, CTSV and CTSB were significantly downregulated in glioma cells treated with ar-turmerone." (PMID 37768200, 2023).
lymph node metastasis (2 papers, 2020 to 2022). "CTSV was glycosylated at N221 and N292 sites and the glycosylation of CTSV is correlated with lymph node metastasis." (PMID 35494076, 2022). "Furthermore, the data also showed that the protein level of total CTSV was significantly higher than that in normal tissues and was correlated with lymph node metastasis as well." (PMID 35494076, 2022).
myasthenia gravis (2 papers, 2022 to 2024). Myasthenia gravis (MG) is a rare, clinically heterogeneous, autoimmune disorder of the neuromuscular junction characterized by fatigable weakness of voluntary muscles. "Abnormal CTSV overexpression in the thymus linked to myasthenia gravis (MG), a condition involving thymic lesions." (PMID 39736788, 2024). "Cathepsin V (CTSV) is a member of the cathepsin family, which is highly expressed in activated macrophages and is involved in inflammatory diseases like myasthenia gravis." (PMID 36601599, 2022).
thymic epithelial tumors (2 papers, 2022 to 2023). "Our results demonstrated that thymic cortical and medullary epithelial markers including β5t, PRSS16, cathepsin V, and AIRE could be used as ancillary markers in the diagnosis and prognosis of thymic epithelial tumors." (PMID 36797681, 2023).